HNF1B (HNF1 homeobox B)
Diseases named in the same sentence as HNF1B in open-access papers (continued):
Sharing a sentence is not in itself a finding about the gene and the disease.
diabetes (continued). "The TCF2 gene (formerly v-HNF1 or HNF-1β) was originally found associated with MODY-type diabetes and with diabetes mellitus, renal cysts and other renal developmental disorders." (PMID 17359527, 2007). "Notably, our analyses indicate HCNE CRMs at monogenic diabetes gene HNF1B and its zebrafish orthologue hnf1ba, both of which are expressed in posterior foregut endoderm." (PMID 41781333, 2026). "Some CNVs, such as the 17q12 [HNF1B] deletion, which causes renal cysts and diabetes, require a different affected cohort since ID is not prominently associated with the CNV." (PMID 41094176, 2026). "There were six patients with the INS variant, four with the ABCC8 variant and one with the HNF1B variant without a family history of diabetes." (PMID 40303944, 2025). "For instance, results in 15% of solved cases facilitated kidney transplant workup, including donor selection, follow-up, diabetes management in pathogenic HNF1B variants, and primary disease recurrence." (PMID 40677324, 2025). "This understanding is fundamental to conceptualizing HNF1B-associated disease as a broader condition, not merely a form of diabetes." (PMID 41009948, 2025). "Frequent VUS variants, such as HNF1B, in this population might explain the over incidence of CKD and diabetes in this population, but need further investigation with functional and experimental data." (PMID 40630292, 2025). "Hereditary forms of diabetes also include rare monogenic variants such as MODY (Maturity-Onset Diabetes of the Young), which follows an autosomal dominant inheritance pattern caused by specific mutations in genes such as HNF4A, GCK, HNF1A, HNF1B, PDX1, and NEUROD1." (PMID 40647303, 2025). "Further large systematic and controlled studies are required in both HNF1B-diabetes and MD." (PMID 39025920, 2024). "The articles represent altogether 293 cases with HNF1B-diabetes and 242 with m.3243 A > G MD." (PMID 39025920, 2024). "Data was extracted from 18 articles for HNF1B-diabetes, 42 for MD, and 2 for both." (PMID 39025920, 2024). "The average time between diagnosis of diabetes and HNF1B-MODY diagnosis was 16.5 years." (PMID 36793123, 2023). "For HNF1B yield in populations selected for diabetes, there were 4 studies." (PMID 37794142, 2023). "The average time between diabetes diagnosis and the diagnosis of HNF1B-MODY was 16.5 years." (PMID 36793123, 2023). "HNF1B-related MODY is a rare form referring to only 1–2% of MODY diabetes cases." (PMID 37511676, 2023). "Although diabetes (in the form of MODY-5) is also frequently observed in HNF1B-deficient patients, the kidney involvement is not related to diabetic dysfunction (i.e., diabetic nephropathy), but rather to an abnormal embryonic development." (PMID 36672242, 2023). "We demonstrate that microduplications are a cause of renal disease but not diabetes and provide evidence that genes other than HNF1B are driving both decreased fluid intelligence and renal function." (PMID 36109160, 2023). "This retrospective observational study in Croatia of individuals diagnosed with HNF1B-related MODY confirms that, in addition to causing diabetes, HNF1B mutations can also lead to a variety of other clinical manifestations, depending on the specific mutation and gene expression." (PMID 37511676, 2023). "We demonstrate 17q12 microdeletions but not microduplications are associated with diabetes in a population-based cohort, likely caused by HNF1B haploinsufficiency." (PMID 36109160, 2023). "Mutations in syndromic diabetes genes other than m.3243A>G and HNF1B were identified in 14 patients but none had clinical features at referral that were suggestive of having mutations in any of these genes." (PMID 34789499, 2022). "HNF1α and HNF1β form homodimers and heterodimers to regulate gene transcription in liver, pancreas, and kidney and HNF1β mutations in MODY5 patients leads to severe diabetes, in part due to the fundamental role of HNF1β in early pancreatic morphogenesis." (PMID 35235779, 2022).
diabetes (continued). "In this study, the diabetes-related genes in the case of early-onset diabetes with a significant family history were examined, and our results showed the presence of the intron mutations of catalase (CAT) gene and hepatocyte nuclear factor 1β (HNF1β) gene." (PMID 35480487, 2022). "Although this variation has not been reported in the literature, in view of the correlation between the HNF1β gene and diabetes and renal impairment, it cannot be ruled out that it may be an important factor in promoting early-onset diabetes and nephropathy." (PMID 35480487, 2022). "The results also showed a modification effect of rs4430796 in HNF1B on the association between high carbohydrate intake (≥65 E%) and incident diabetes only in men; however, this effect did not remain significant after FDR correction." (PMID 35277013, 2022). "The age at diagnosis of diabetes was higher in HNF4α- and HNF1β-MODY probands than in the other MODY types, including MODY X. MODY X probands exhibited higher fasting glucose levels and glucose levels at 60 min during an OGTT compared with those of GCK-, HNF1α-, and HNF4α-MODY probands." (PMID 34746319, 2021). "Similarly, the presence of renal/pancreatic abnormalities in young patients with diabetes are suggestive for genetic testing for HNF1B-MODY." (PMID 34299172, 2021). "Our mutational analysis of only GCK, HNF4α, HNF1α, and HNF1β genes is not sufficient to strictly confirm the susceptibility mutation in patients with an onset of diabetes at an early age." (PMID 34746319, 2021). "Diabetes in HNF1B-MODY develops during adolescence or early adulthood." (PMID 32528556, 2020). "HNF1B gene played the important role in the primary pathophysiology of diabetes." (PMID 32329795, 2020). "The phenotype caused by HNF1B mutations is diverse and does not necessarily lead to the onset of diabetes." (PMID 31056860, 2019). "In 33 (13%) patients, class 4–5 variants were identified in one of four genes usually considered as rarely involved in monogenic diabetes in adults, namely HNF1B (15 cases, 6.0%, among which 10 HNF1B whole-gene deletion), ABCC8 (8 cases, 3.2%), KCNJ11 (3 cases, 1.2%), and INS (7 cases, 2.8%)." (PMID 31291970, 2019). "This patient's father also had a heterozygous mutation at the same HNF1B gene site; however, the father had normal bilateral kidney morphology with no history of diabetes mellitus." (PMID 31056860, 2019). "The father of P45 also had an HNF1B mutation, however, he did not have diabetes mellitus or renal structural abnormalities, and we have not functionally validated this mutation site." (PMID 31056860, 2019). "Of the three patients with the HNF1B mutation we detected, P44 (32 years old) had type 2 diabetes, while P43 (56 years old) and P45 (39 years old) had no diabetes." (PMID 31056860, 2019). "In this study, our aims were to measure faecal elastase-1 in patients with HNF1B-associated disease regardless of diabetes status and assess the degree of symptoms associated with pancreatic exocrine deficiency." (PMID 30094008, 2018). "In this report, we describe a rare damaging missense mutation in HNF1β that was identified in a proband with early-onset atypical diabetes with no morphological renal tract anomalies." (PMID 29764441, 2018). "We measured faecal elastase-1 in patients with HNF1B-associated disease regardless of diabetes status and assessed the degree of symptoms associated with pancreatic exocrine deficiency." (PMID 30094008, 2018). "In summary, faecal elastase-1 deficiency is an important feature of HNF1B-associated renal disease even when diabetes is not present." (PMID 30094008, 2018). "However, the data suggests that the antenatal detection of renal hyperechogenicity or cysts plus the presence of either diabetes or pancreatic hypoplasia in children should prompt clinicians to consider a diagnosis of HNF1B-related disease." (PMID 26022541, 2015).
diabetes (continued). "Unlike, HNF1A and HNF4A monogenic diabetes, pancreatic atrophy is common in those with HNF1B mutations, therefore carriers do not display the same sensitivity to SU therapy and often require insulin therapy." (PMID 23766565, 2013). "Insulin therapy is usually required in those with HNF1B diabetes due to pancreatic atrophy." (PMID 24705260, 2013). "However, we were not able to find any pathogenic mutations in either HNF1B or other genes reported to be associated with monogenic diabetes." (PMID 40166445, 2025). "There is a rationale for studying SGLT2i specifically in HNF1B-diabetes, as it might improve the renal outcome of the associated non-diabetes-related kidney disease." (PMID 39025920, 2024). "However, in HNF1B-MODY there is a combination of insulin deficiency and hepatic insulin resistance, explaining why they often require insulin therapy in the first years after diabetes diagnosis." (PMID 36793123, 2023). "In this context one could suspect a hybrid diabetes (type 1 diabetes and HNF1B-MODY)." (PMID 36793123, 2023). "Thus, the aim of our study was to define the serum metabolomic fingerprint of HNF1B mutations independent of coexisting diabetes and kidney disease and to understand its role in the disease pathogenesis." (PMID 35179657, 2022). "In addition to the marked heterogeneity of the urogenital phenotype observed in association with diabetes, many cases of HNF1B without diabetes have been described." (PMID 32528556, 2020). "Faecal elastase-1 deficiency is a common feature of HNF1B-associated renal disease even when diabetes is not present and pancreatic exocrine deficiency may be more symptomatic than previously suggested." (PMID 30094008, 2018). "If indeed an HNF1B-MODY-specific miRNA expression pattern could be identified, it could bolster the current diagnostic strategies of monogenic diabetes, which involve the application of statistical tools to stratify candidates for genetic screening, or biomarkers." (PMID 27059371, 2016). "This differs from studies in England and France, where HNF1B and MIDD are the most common syndromic diabetes etiologies, likely reflecting the highly consanguineous nature of our cohort." (PMID 40746173, 2026). "Our prediction model focuses on detecting common MODY subtypes (GCK‐, HNF1A‐, HNF4A‐ and HNF1B‐MODY), which account for over 80% of monogenic diabetes reported in Chinese." (PMID 40966384, 2025). "MD subtypes are many but most patients bear defects in four of the Maturity Onset Diabetes of the Young (MODY) genes: GCK, HNF1A, HNF4A, HNF1B." (PMID 40244428, 2025). "In the PERT group, 9 subjects (19%: 2 subjects with T1D, 3 with pancreatogenic diabetes, 2 with MODY HNF-1B and one undetermined) had notable hyperglycemia in the months after PERT initiation." (PMID 38331895, 2024). "Despite being a rare disease, HNF1B-MODY is underdiagnosed and often classified as another type of diabetes." (PMID 36793123, 2023). "The genetic content of the monogenic diabetes NGS panel used is recommended to include at least the 5 common diagnoses (GCK, HNF1A, HNF1B, HNF4A, and m.3243A>G)." (PMID 37033247, 2023). "The median age at diabetes diagnosis was 28 (IQR 24) years and the median age at HNF1B-MODY diagnosis was 40.5 (IQR 23) years." (PMID 36793123, 2023). "Hepatocyte nuclear factor-1 beta (HNF1B)-MODY, also called RCAD (renal cysts and diabetes syndrome) or MODY 5, is characterized by a variable coexistence of diabetes and congenital abnormalities of kidneys and urinary tract (CAKUT)." (PMID 35179657, 2022). "As a result, HNF1B-MODY patients can develop abnormalities in all of these organs in addition to hyperglycaemia, the symptoms of which often precede the diabetes." (PMID 34440499, 2021). "In both T1D and T2D, we found enrichment of monogenic forms of diabetes, as expected —2 genes in T1D (RASGRP1, INS) and 8 in T2D (HNF1B, GCK, WFS1, KCNJ11, ABCC8, HNF1A, PPARG, SLC2A2)." (PMID 33836063, 2021).
diabetes (continued). "Pubmed was searched for publications on the subject by employing search terms: MODY, Maturity Onset Diabetes of the Young, monogenic diabetes, HNF1A, HNF-1 alpha, GCK, glucokinase, HNF1B, HNF-1 beta, HNF4A, HNF-4 alpha, biomarkers." (PMID 32528556, 2020). "Based on early diabetes development, the absence of type 1 diabetes (T1D) antibodies, the presence of renal dysgenesis and a relevant history of atypical diabetes in her family, MODY5 was suspected and sequencing of the hnf1b gene was requested." (PMID 32864159, 2020). "Therefore, we sequenced the entire coding sequence and exon/intron boundaries of the Hnf-1β gene, which is responsible for MODY5 exhibiting diabetes and renal malformation in humans, and found no mutation in the Hnf-1β gene of affected rats in the DEK strain (data not shown)." (PMID 31467929, 2019). "Furthermore, it is important to emphasise that clinicians should maintain a high index of suspicion for monogenic diabetes in young onset non-autoimmune disease, and should consider referral for HNF1β mutation analysis in the presence of renal cysts with or without diabetes." (PMID 29764441, 2018). "Finally, our small sample size of 29 individuals with HNF1B-associated disease means we may have been underpowered to make definitive comments on the comparison of patients with and without diabetes." (PMID 30094008, 2018). "Since many pediatric 17q12del carriers in the NMR were referred for testing due to structural renal anomalies without diabetes, HNF1B screening should be considered in children with renal/extra-renal features, irrespective of diabetes or autoantibody status." (PMID 42278591, 2026). "This enrichment was lower than observed in T2D cases and independent of parental diabetes history and after removing variants in HNF1A, HNF4A or HNF1B genes from the PGS (0.4 s.d." (PMID 40925988, 2025). "The study suggests routine testing of syndromic monogenic diabetes genes, particularly m.3243 A > G and HNF1B, in patients with suspected MODY who do not exhibit typical genetic syndrome features." (PMID 39835172, 2025). "Most reported patients with HNF1B-diabetes (N = 293) and MD (N = 233) are on insulin without treatment studies." (PMID 39025920, 2024). "There are no RCTs on HNF1B-diabetes or MD and even open treatment studies and cohort or case reports are few." (PMID 39025920, 2024). "While insulin has been advocated as the choice of treatment for both HNF1B-diabetes and MD4,127, we found no systematic evidence favoring the use of insulin." (PMID 39025920, 2024). "There is no defined precision treatment approach or even clear first-line medication for MD or HNF1B-diabetes, with the evidence for specific treatment in HNF1B-diabetes and MD being of low quality with no trials and very few studies." (PMID 39025920, 2024). "In the UK study, those referred for monogenic diabetes who had no other common etiology detected received HNF1B sequencing and doseage analysis." (PMID 37794142, 2023). "HNF1B-MODY express variable multisystemic phenotypes with a wide spectrum of pancreatic and extra-pancreatic clinical manifestations, ranging from isolated diabetes or kidney disease to multiorgan disorders." (PMID 36793123, 2023). "Family 4 The female patient with HNF1B gene exon deletion had a negative family history of diabetes or kidney diseases." (PMID 37511676, 2023). "Nowadays, it is known that several other organs and systems can be affected by the perturbation of the HNF1B signaling, and that diabetes and renal cysts are not always present." (PMID 36672242, 2023). "One clinician failed to report renal cysts for an HNF1B diabetes patient, and deafness in another patient with the m.3243A>G mutation." (PMID 34789499, 2022). "This testing strategy is reflected by the lack of comprehensive inclusion of syndromic diabetes genes (with the exception of HNF1B) in gene panels for MODY testing in the NCBI gene testing registry." (PMID 34789499, 2022).
diabetes (continued). "HNF1β mutations have been associated with isolated renal disease in the absence of diabetes and conversely, HNF1β deletions with young-onset diabetes but no kidney disease have also been described." (PMID 29764441, 2018). "Faecal elastase-1 was low in 7/15 (47%) HNF1B patients without diabetes compared with 11/14 (79%) of those with diabetes (P = 0.1)." (PMID 30094008, 2018). "We included 15 HNF1B patients without diabetes in this study; 7/15 (47%) had a low faecal elastase-1 measurement but only 1/15 (7%) had a measurement of <200 μg/g stool." (PMID 30094008, 2018). "Overall, faecal elastase-1 levels were low in 7/15 (47%) HNF1B patients without diabetes compared with 11/14 (79%) of those with diabetes (P = 0.1)." (PMID 30094008, 2018). "A final limitation is that we have investigated the prevalence of HNF1A-MODY only, as the most common form of monogenic diabetes, so the prevalence of other MODY subtypes, such as GCK-, HNF4A- or HNF1B-MODY in Croatia remains unknown." (PMID 29666556, 2018). "In the paediatric population, the frequency of other clinical features and a positive family history of renal disease or diabetes did not vary between patients with and without a diagnosis of HNF1B-related disease." (PMID 26022541, 2015). "We also observed a potential interaction between HNF1B SNPs and diabetes status in the WHI, but not in the MEC." (PMID 22299039, 2012). "A previous study conducted in CPS-II and PLCO found that diabetes did not mediate the association between JAZF1 and HNF1B/TCF2 SNPs and prostate cancer risk, and we observed no statistical interaction between diabetes and three SNPs in HNFIB/TCF2." (PMID 21390317, 2011). "Therefore, syndromic genes, particularly HNF1B, should be included in gene panel testing for individuals with suspected monogenic diabetes, even if they present a pure diabetes phenotype rather than the classical syndromic presentation." (PMID 39976628, 2025). "There were no randomized studies or trials of treatment in HNF1B-diabetes." (PMID 39025920, 2024). "However, several other organs and systems have since emerged as being affected by HNF1B defect, while diabetes and renal cysts are not always present." (PMID 36672242, 2023). "For example, neonatal onset (directed neonatal diabetes gene panel testing); retrospective mild fasting hyperglycaemia (characteristic of GCK); high HDL (HNF1A); neonatal macrosomia (HNF4A) and syndromic features present in patients with either HNF1B or mitochondrial forms (MIDD)." (PMID 37033247, 2023). "However, these criteria are often not specific for the HNF1β subtype of ADTKD and bear the risk of not identifying the patients that initially present with diabetes or electrolyte phenotype." (PMID 35554666, 2022). "As an example, mice with heterozygous deletions of Hnf1a, Hnf4a, or Hnf1b do not develop diabetes." (PMID 34450036, 2021). "Diabetes might present as new-onset diabetes after transplantation (NODAT); prior analysis of the hnf1b gene should be considered in all individuals with unexplained congenital anomalies of the kidneys and urinary tract undergoing renal transplantation to improve post-transplant management." (PMID 32864159, 2020). "HNF-1β (HNF1 homeobox B) mutations may be associated with nondiabetic renal dysfunction and diabetes in Chinese and Italian patients, but this gene is considered to be involved in T2D." (PMID 19471607, 2008). "However, recent studies have shown that syndromic monogenic diabetes genes (particularly m.3243A > G, HNF1B and WFS1) are more common than previously thought and usually lack their typical syndromic clinical features, presenting overlapping diabetes phenotypes with non‐syndromic monogenic diabetes." (PMID 35822264, 2022). "However, caution must be applied when interpreting the results between the HNF1B cohorts with and without diabetes, as any differences may reflect the discrepancy in age between the two groups." (PMID 30094008, 2018).